RORA (RAR related orphan receptor A)
Diseases named in the same sentence as RORA in open-access papers (continued):
Sharing a sentence is not in itself a finding about the gene and the disease.
ovarian carcinoma (continued). "Therefore, we conclude that PS VII may hinder the binding of ECM1 to VEGFR2 and inhibit the FAK/AKT/GSK3β signaling pathway in PARP inhibitor-resistant ovarian cancer cells by activating RORα, affecting functions such as glycolysis and angiogenesis, and ultimately improving its resistance treatment." (PMID 38725854, 2024). "A total of 232 high-grade serous ovarian cancer patient tissue chips (including 114 PARP inhibitor-resistant patients and 118 PARP inhibitor-sensitive patients) were selected to evaluate the clinical significance of RORα, ECM1, and VEGFR2 in ovarian cancer." (PMID 38725854, 2024). "Mechanistically, we found that VII can bind to RORα, enhance its protein stability, and inhibit the FAK/AKT/GSK3β signaling pathway in ovarian cancer cells resistant to PARP inhibitors through the RORα/ECM1/VEGFR2 signaling axis." (PMID 38725854, 2024). "The experimental results showed that the inhibitory ability of PS VII towards the migration and invasion ability of ovarian cancer SKOV3 PARPi-R and HEY PARPi-R cells was similarly diminished after downregulating RORα expression." (PMID 38725854, 2024). "PS VII, a targeted drug for the RORα/ECM1/VEGFR2 signaling axis, is expected to become a new generation of ovarian cancer therapeutic agents." (PMID 38725854, 2024). "In our research, we found that PS VII can bind to RORα and enhance its protein stability, thereby inhibiting glycolysis, angiogenesis, and PARP inhibitor resistance in ovarian cancer." (PMID 38725854, 2024). "Both WB and immunofluorescence (IF) analyses showed expression of VDR, RORγ, and RORα in OVCAR-3 and SKOV-3 ovarian cancer cells, with the latter showing significantly stronger levels of expression." (PMID 33227893, 2020). "The analysis results showed that in the tissue samples of ovarian cancer patients resistant to PARP inhibitors, 8.7% (10/114) showed "High" expression of RORα, 21.0% (24/114) showed "Moderate" expression, 36.6% (36/114) showed "Weak" expression, and 38.6% (44/114) showed "Negative" expression." (PMID 38725854, 2024). "In the tissue samples of ovarian cancer patients sensitive to PARP inhibitors, 34.7% (41/114) showed "High" expression of RORα, 26.3% (31/114) showed "Moderate" expression, 23.7% (28/114) showed "Weak" expression, and 15.3% (18/114) showed "Negative" expression." (PMID 38725854, 2024). "However, the role of RORα in ovarian cancer is not yet clear." (PMID 38725854, 2024).
schizophrenia (6 papers, 2009 to 2023). A major psychotic disorder characterized by abnormalities in the perception or expression of reality. "We then focus on how RORα is linked to NDDs, particularly ASD and schizophrenia, and how its diverse extra-cerebral actions can explain the systemic components of these diseases." (PMID 37066074, 2023). "Further indications for a link between RORα and ASD came from a recent study demonstrating that the microRNA MIR137, which has been implicated in ASD and schizophrenia, targets the 5’-UTR of RORα." (PMID 26878025, 2015). "For example, there is greater PFC oxidative stress in schizophrenia and ASD, but there is also less PFC RORα expression in these disorders, which can directly explain the greater oxidative stress without involving the cerebellum." (PMID 37066074, 2023). "Lastly, RORα binds to Bmal1 and Cry and is a central part of the circadian cycle, a cycle known to be disrupted in ASD and schizophrenia patients." (PMID 37066074, 2023). "Finally, it is important to note that RORB, RORA, and DBP were identified by us recently as possible genes involved in schizophrenia using a pharmacogenomic mouse model and CFG approach." (PMID 19909500, 2009). "But the role of RORα is not confined to ASD; its expression is altered in schizophrenia and many of its single nucleotide polymorphisms are found in ADHD." (PMID 37066074, 2023).
allergic asthma (5 papers, 2013 to 2025). A asthma with a basis in a pathological type I hypersensitivity reaction. "It has also been reported that RORα regulates Th2 cellular responses in allergic asthma." (PMID 37387671, 2023).
atopic dermatitis (5 papers, 2015 to 2023). "RORα expression was also found to be significantly elevated in skin from patients with atopic dermatitis (AD), while in an experimental model of AD-like inflammation RORα-deficient mice exhibit a profound deficit in ILC2 cells and significantly reduced allergic skin inflammation." (PMID 26878025, 2015). "For example, the expression of RORα in resident T cells in the skin can upregulate the expression of DR3, promote T cell function, and inhibit allergic dermatitis." (PMID 34177881, 2021). "Skin Treg cells express high RORα levels, with Treg-specific Rorα deletion accelerating the inflammation induced by innate lymphocyte 2 (ILC2) and Th2 cells in an atopic dermatitis mouse model." (PMID 31434282, 2019). "Therefore, the RoRα and TL1a-DR3 pathways can be used as therapeutic targets for allergic dermatitis." (PMID 34177881, 2021).
Autoimmunity (5 papers, 2017 to 2025). The occurrence of an immune reaction against the organism's own cells or tissues. "Our current study, by identifying RORα as a key regulator of the sustained Th17 effector program, suggests that targeting this receptor could be a viable strategy for treating autoimmune pathologies linked to Th17 effector functions in chronically inflamed patient tissues." (PMID 36243007, 2022). "Importantly, as a member of the nuclear receptor superfamily, RORα is a ligand-regulated transcription factor and targeting of this receptor in vivo not only inhibits the development of autoimmunity, it effectively suppresses active inflammation." (PMID 33397953, 2021). "Here we used a combination of genetic, molecular biology, and pharmacological approaches to demonstrate that RORα is a major regulator of TH17 cell development, autoimmunity, and chronic inflammation." (PMID 33397953, 2021). "Since redundancy suggests dispensable or unnecessary, our data indicates that RORα is a requisite factor for TH17 cell differentiation and the development of autoimmunity." (PMID 33397953, 2021). "The orphan nuclear receptors retinoic acid-related receptor α and γt (RORα and RORγt) are critical in the development of T helper 17 (Th17) cells, and ROR-specific synthetic ligands have proven efficacy in several mouse models of autoimmunity." (PMID 30189901, 2018). "Together, these data suggest that RORα functions independent of RORγt in programming TH17 pathogenicity and identifies RORα as a safer and more selective therapeutic target for the treatment of TH17-mediated autoimmunity." (PMID 33397953, 2021).
heart failure (5 papers, 2020 to 2025). Inability of the heart to pump blood at an adequate rate to meet tissue metabolic requirements. "Deficiency of RORα leads to reduced contractility of the heart and heart failure in both human and mouse heart models of hypertrophy." (PMID 39518891, 2024).
Hepatic fibrosis (5 papers, 2019 to 2026). The presence of excessive fibrous connective tissue in the liver. "It has been shown that RORα directly transcribes the Ccl5 and Cxcl10 genes through its response element REORE that is associated with liver fibrosis." (PMID 40940746, 2025). "The study results suggest that miRNA-30 may augment schistosomiasis-induced hepatic fibrosis through a probable interaction with the host RORA." (PMID 39139565, 2024). "Mechanistically, the orphan nuclear receptor RAR-related orphan receptor alpha (RORα) activates the expression of the liver fibrosis-related chemokines C-C motif chemokine ligand 5 (CCL5) and C-X-C motif chemokine ligand 10 (CXCL10), which is suppressed by the Mediator subunit MED23." (PMID 31805036, 2019). "Among these, the mRNA levels of nine genes, including USB1, NT5E, RORA, SDK1, and IL10, were significantly up-regulated, suggesting their involvement in the miRNA-30-mediated regulation of host hepatic fibrosis." (PMID 39139565, 2024). "Both the comprehensive transcriptome analysis and in vitro assays indicate that RORα, one member of the ROR family, is the partner of MED23 in the pathogenesis of liver fibrosis." (PMID 31805036, 2019). "Our study demonstrated that hepatic RORα, in cooperation with MED23, plays a role in inflammatory responses, acting as a positive regulator of CCL5 and CXCL10 in initiating the liver fibrosis, which suggests new molecular targets for clinical intervention in liver fibrosis." (PMID 31805036, 2019).
myocardial infarct (5 papers, 2020 to 2024). "Deficiency in RORα was found to lead to a significant increase in the magnitude of myocardial infarcts, marked elevation of myocardial apoptosis, and aggravated contractile dysfunction." (PMID 39518891, 2024). "Moreover, it has been revealed that the high expression of RORA correlates with acute myocardial infarction, which may be an independent risk factor for acute myocardial infarction." (PMID 35934844, 2022). "Long noncoding RNA FGD5‐AS1 suppressed hypoxia‐induced oxidative stress and inhibited apoptosis of cardiomyocytes in acute myocardial infarction by upregulating the expression of RORA." (PMID 35195816, 2022). "In addition, RORα agonist augmented the protective effect against myocardial infarct by remote ischemic perconditioning (RIPerC) in both non-pinealectomized and pinealectomized mice." (PMID 36834872, 2023).
osteoarthritis (5 papers, 2021 to 2023). A noninflammatory degenerative joint disease occurring chiefly in older persons, characterized by degeneration of the articular cartilage, hypertrophy of bone at the margins and changes in the synovial membrane. "Retinoid-related orphan receptor alpha (RORA), a member of orphan nuclear receptors (ONRs), has been proved to be associated with multiple biological processes and diseases, such as lipid metabolism, osteoarthritis, circadian rhythm, and cancers." (PMID 35504868, 2022). "Previous studies suggested that RORA plays a contributory role in the pathogenesis of osteoarthritis by regulating cholesterol metabolism and IL6/STAT3 pathway." (PMID 36380336, 2022). "Retinoic acid-related orphan receptor α (RORα) was found to mediate the induction of osteoarthritis by alterations in cholesterol metabolism, which acts as downstream receptor of cholesterol hydroxylases, including cholesterol 25-hydroxylase (CH25H) and 25-hydroxycholesterol 7α-hydroxylase (CYP7B1)." (PMID 34149433, 2021).
osteoporosis (5 papers, 2012 to 2023). A condition of reduced bone mass, with decreased cortical thickness and a decrease in the number and size of the trabeculae of cancellous bone (but normal chemical composition), resulting in increased fracture incidence. "Application of cholesterol sulfate, a RORα agonist, prevented bone mass loss in the inflammation-mediated or ovariectomy (OVX) -mediated osteoporosis models." (PMID 38027103, 2023). "For example, bisphenol A inhibits osteoblast differentiation and bone formation by activating RORα, leading to the formation of osteoporosis." (PMID 38260098, 2023).
Parkinson disease (5 papers, 2011 to 2025). A progressive degenerative disorder of the central nervous system characterized by loss of dopamine producing neurons in the substantia nigra and the presence of Lewy bodies in the substantia nigra and locus coeruleus. "We found that target genes of RORA were significantly enriched in pathways related to different neurodegenerative conditions, such as Parkinson disease (q = 0.010) and AD (q = 0.047)." (PMID 39184089, 2024). "RORA has been reported to exert neuroprotective effects in Parkinson's disease; however, its role in modulating pathological α‐Syn spreading remains unclear." (PMID 40433888, 2025).
steatosis (5 papers, 2016 to 2023). Increased lipid within the cytoplasm of cells. "Alteration in CCR7, IMPDH2, IL6ST, MYC, LPIN1, PDE7A and RORA was significantly associated with hepatotoxicity including liver damage, -hyperplasia, -inflammation, -steatosis, -fibrosis, -necrosis and -proliferation." (PMID 26907258, 2016). "While the expression of other candidates, including RORA, RORC, and THRB, remained unchanged, that of PPARA significantly decreased as NAFLD progressed to steatosis and NASH, and showed a negative correlation with that of MIR20B." (PMID 34964438, 2021).
allergic disease (4 papers, 2013 to 2025). An immune response that occurs following re-exposure to an innocuous antigen, and that requires the presence of existing antibodies against that antigen. "ROR inhibitors have been shown to be effective in suppressing EAE, driven by RORγt-expressing Th17 cells, and their efficacy in targeting RORα during allergy and asthma awaits investigation." (PMID 23562755, 2013). "The identification of RORα as a critical transcription factor in ILC2 development offers the possibility of targeting this regulator to block ILC2 generation and ameliorate allergic disease." (PMID 23562755, 2013).
Anxiety (4 papers, 2022 to 2025). Intense feelings of nervousness, tension, or panic often arise in response to interpersonal stresses. "For example, the RARB:RXRG dimer’s activities in amygdala have been linked to expression of anxiety-related phenotypes, and RORA is associated with enhanced fear response in humans and mice." (PMID 35192674, 2022).
COVID-19 (4 papers, 2020 to 2024). A disease caused by infection with severe acute respiratory syndrome coronavirus 2. "The genetic variant associations in RORA, SLC12A6, and SLC6A19 genes were observed in genome-wide association study (GWAS) of COVID-19 susceptibility." (PMID 34512723, 2021). "Three genes—RORA, SLC12A6, and SLC6A19—showed associations with multiple COVID-19 phenotypes." (PMID 34512723, 2021). "Furthermore, the GWAS of hospitalized COVID-19 identified 3p21.31 locus, wherein the genome-wide significant variant—rs13325613 (chr3:46298373bp; p = 1.17e-08) is a trans-QTL for genes RORA (p = 7.7e-7) and RORC (p = 1.3e-31)." (PMID 34512723, 2021). "As the occurrence of cardiovascular events during COVID-19 suggests that targeting the endothelium is part of the viral infection course, we surmise COVID-19 patients who have a pre-existing genetic propensity for low SON, OGT, and RORA expression may therefore be more susceptible to cardiac damage." (PMID 33240937, 2020).
Hyperglycemia (4 papers, 2015 to 2022). An increased concentration of glucose in the blood. "We conclude that hyperglycemia induces RORA suppression through epigenetic modification and the subsequent dissociation of Oct3/4 from the RORA promoter." (PMID 35027651, 2022). "Our in vitro study through human neural progenitor cells showed that RORA expression was suppressed through hyperglycemia-induced epigenetic modification on the RORA promoter." (PMID 35027651, 2022). "Genetic studies have shown that attenuated RORα leads to various metabolic abnormalities in mice, including hyperglycemia and glucose intolerance." (PMID 34183658, 2021). "Expression of a dominant-negative RORα in skeletal muscle induced mild hyperglycemia and glucose intolerance and attenuated insulin-mediated phosphorylation of Akt2." (PMID 26878025, 2015). "In addition, a RORα inverse agonist suppresses insulitis and prevents hyperglycemia in a mouse model of type 1 diabetes." (PMID 26383638, 2015). "In this study, we show that transient hyperglycemia-mediated oxidative stress suppresses the expression of RORA, CYP19A1, and SOD2; prenatal RORA deficiency mimics maternal diabetes-mediated ALB, and postnatal RORA manipulation in the amygdala modulates maternal diabetes-mediated ALB in offspring." (PMID 35027651, 2022). "The reporter assay showed that hyperglycemia-induced reporter suppression disappeared in two of the OCT mutation constructs (located at −276 and −251, respectively, marked in green), suggesting that hyperglycemia mediates RORA suppression through the OCT binding motif on the RORA promoter." (PMID 35027651, 2022). "In addition, we showed that Oct3/4 was dissociated from the RORA promoter with subsequent RORA suppression in the presence of transient hyperglycemia, indicating that Oct3/4 may play an important role in neural development by regulation of RORA expression, which is consistent with previous findings." (PMID 35027651, 2022). "Recently, the RORα/γ inverse agonist SR1001 was shown to suppress insulitis and prevent hyperglycemia in a mouse model of type 1 diabetes." (PMID 26878025, 2015).
Hypertension (4 papers, 2021 to 2025). The presence of chronic increased pressure in the systemic arterial system. "RORα mRNA expression was decreased in Th17 cells from angiotensin II (Ang II)-induced mice with hypertension." (PMID 36834872, 2023). "The potential clinical application prospect of RORα for other common types of hypertension needs to be further verified and clarified." (PMID 36834872, 2023). "This suggests that there may be a correlation between RORα and hypertension." (PMID 36834872, 2023). "Therefore, the causal relationship between RORα and hypertension is not known well." (PMID 36834872, 2023).
periodontitis (4 papers, 2017 to 2025). An acute or chronic inflammatory process that affects the tissues that surround and support the teeth. "The present study suggests that IL-35 could directly suppress IL-17 expression via RORα and RORγt inhibition and might play an important role in inflammatory diseases such as periodontitis." (PMID 28229025, 2017). "The present study suggests that IL-35 could directly suppress IL-17 expression via RORα and RORγt inhibition to restrain the excessive immune response in inflammatory conditions such as periodontitis." (PMID 28229025, 2017). "Periodontitis in adults resulted in decreased levels of CSNK1D, RORA, CLOCK, DBP, NR1D1, ID2, and PER3 and a substantial increase in expression of FOS." (PMID 36472983, 2022).
skin inflammation (4 papers, 2019 to 2024). "To address the significance of epidermal RORα, we recently generated a mouse strain with an epidermis-specific Rora deletion (RoraEKO), and we found that MC903-induced AD-like skin inflammation was greatly enhanced with an epidermal RORα deficiency." (PMID 39409027, 2024). "In this study, ILC2 depletion by RORα-deficient bone marrow transplantation markedly improved dermatitis, indicating that keratinocyte-derived IL-33 causes atopic inflammation through ILC2 activation." (PMID 35757747, 2022). "The epidermal RORα deficiency increased the TEWL rate at a steady state and exacerbated skin inflammation in the ACD mouse model." (PMID 39409027, 2024). "In vitro and in vivo studies are needed to uncover the specific roles of RORα target genes in skin barrier function and skin inflammation, focusing on the genes related to pathological conditions." (PMID 39409027, 2024). "To verify the essential roles of epidermal RORa in MC903-induced skin inflammation, we generated a Roraflox/flox strain and a RoraLacZΔ/+; K14-CRE strain from the Roratm1a/+ mice." (PMID 37373387, 2023). "Therefore, epidermal RORα may have dual actions in preventing skin inflammation by maintaining barrier integrity and suppressing the innate immune response of keratinocytes." (PMID 39409027, 2024). "Furthermore, deletion of RORα, which is necessary for the ILC2 development, significantly improved MC903-induced dermatitis, indicating that ILC2s are essential for MC903-induced atopic inflammation." (PMID 35757747, 2022).
type 2 diabetes (4 papers, 2013 to 2020). "A role for RORα in the regulation of insulin sensitivity is supported by a study showing an association between a single nucleotide polymorphism in RORα (rs7164773) and an increased risk for type 2 diabetes in the Mexico Mestizo population." (PMID 26878025, 2015).